Y_RNA (Y RNA )
Gene: Miscellaneous RNA gene on chromosome 12 (108,738,484 to 108,738,604, forward strand). Ensembl gene ENSG00000200060.
Homologues: Orthologues: chimpanzee Y_RNA (100% identical), macaque Y_RNA (95% identical). Paralogues in human: RNY1 (79% identical), Y_RNA (78% identical), Y_RNA (77% identical), RNY1P7 (76% identical), Y_RNA (76% identical), Y_RNA (75% identical), Y_RNA (74% identical), RNY1P10 (74% identical), RNY1P11 (74% identical), RNY1P8 (73% identical), Y_RNA (73% identical), Y_RNA (72% identical), and 90 more.